IL1B (interleukin 1 beta)
Diseases named in the same sentence as IL1B in open-access papers (continued):
Sharing a sentence is not in itself a finding about the gene and the disease.
infection (continued). "Representative pro-inflammatory cytokines, including IL-1β, IL-6, and TNF-α, are secreted upon infection and tissue damage, promoting the migration of immune cells to the inflammatory site and amplifying the inflammatory response." (PMID 39727927, 2024). "According to Grimble39, it is considered beneficial the presence of cytokines (e.g. IL-1β and TNF-α) in adequate concentrations during an inflammatory response to infection." (PMID 38789563, 2024). "For example, EV-A71 infection activates the NLRP3 inflammasome in macrophages and promotes the production of IL-1β to increase vascular permeability." (PMID 39767680, 2024). "The secreted form of the protein encoded by this gene is known to be increased in response to stress and inflammatory mediators such as IL1B, IFNG, or TNF, as well as upon infection with bacteria and viruses such as SARS-CoV-2." (PMID 39337540, 2024). "The probiotics induced the expression of immune-related genes such as IL-8, IL-1β, TNF-α, TLR-2, C3, IFN-γ, and MHC I. Additionally, these treatments increased the survival rates of grey mullet following infection with N. seriolae." (PMID 39563419, 2024). "Infection of BMDMs with Leishmania has been reported to trigger NLRP3 inflammasome activation, leading to the release of mature IL-1b." (PMID 39696675, 2024). "A key limitation was the exclusion of pro-inflammatory cytokines, such as IL-1β and NLRP3, which are gold standards for distinguishing between general inflammation and infection." (PMID 39590856, 2024). "After the piglets were challenged with G. parasuis for 48 h, the IL-1β, IL-10, IL-18, TNF-α and IFN-γ mRNA expression levels in the blood of the infection group were significantly greater than those in the blood of the control group (p < 0.01)." (PMID 39075542, 2024). "Compared with WT/Vector strain, infection with the WT/PrrH and the ΔprrH/PrrH strains increased the expression of tumor necrosis factor-α (TNF-α) and interleukin-1β (IL-1β)." (PMID 38289930, 2024). "Infection triggered a T helper-type 1 immune response supported by the detection of pro-inflammatory cytokines such as IFN-γ, IL-1β, IL-6, IL-12p40 and IL-17 in the supernatant of lung homogenates." (PMID 38198478, 2024). "After 48 h post-infection, the gene expression of IL-1β and TNF-α expression significantly decreased compared with 3-h post-infection." (PMID 38965554, 2024). "Our data shows an increase in TNF-α and IL-6 but a decreased expression in IL-1β and IL-8 post DLD-1 infection." (PMID 39427065, 2024). "First, we determined the quantity of production for IL-1β, IL-6, and TNF-α in the lung as the primary site of infection." (PMID 38646937, 2024). "Therefore, it would be interesting to determine how host immunity could be differentially triggered in infections with different M. tuberculosis strains through the activation of some of the pathways identified in this pilot study and the overexpression of IL-1β." (PMID 39597535, 2024). "At 24 h post-infection, both berbamine and tetrandrine significantly reduced TNF-α, IL-1β, and IL-6 levels compared to the ASFV control by around 60–80%." (PMID 38664855, 2024). "E. tenella infection lead to upregulation of pro-inflammatory cytokines as IFN-γ, IL-1β, IL-6 and anti-inflammatory cytokines as TGF-β4 following primary infection, while their expression was downregulated following secondary infection." (PMID 38492183, 2024). "Compared with infection alone, levamisole and BMS-1 reduced IL-1β, IL-10, IL-18, TNF-α and IFN-γ mRNA expression and increased IL-2 and IL-8 mRNA expression (P < 0.01)." (PMID 39075562, 2024). "The mammalian antiviral immune responses induced by type I IFNs and proinflammatory cytokines, including IL-1β and TNF-α, represent the first line of host defense upon infection." (PMID 38501350, 2024). "Then, we monitored the amount of pro-inflammatory cytokines interleukin-1β (IL-1β), IL-18 and tumor necrosis factor-α (TNF-α) during infection." (PMID 39376663, 2024).
infection (continued). "Taken together, ITA and its isomers MES and CTC have an overall similar immunomodulatory effect on production of the cytokines IL6, TNFα, IL1β and IL10 in response to infection with C. burnetii." (PMID 39156902, 2024). "Compared to the WT NMII-infected MBMDM, the Tn::icmE and Tn::dotA infections resulted in increased secretion of TGF-β1 and reduced the level of IL-1β in MBMDM." (PMID 38787259, 2024). "Cytokines such as IL-1β and TNF produced following infection were shown to directly inhibit the dorsal raphe nucleus in the brain, which is responsible for wakefulness and to activate the POA/basal forebrain region that promotes nonrapid eye movement sleep." (PMID 39107476, 2024). "Inflammatory cytokine assays demonstrate that compared to the mock group, IL-1β, IL-6, IL-8, and TNF-α were significantly upregulated in the lungs, spleen, intestines, and brain post-infection." (PMID 39170631, 2024). "Taken together, our results highlight the distinctive and dynamic patterns of IFN-α, IFN-β, IL1-β, IL-6, and iNOS mRNA expressions in response to IBV DMV/1639 infection, underscoring the intricate interplay between the virus and the host TOCs." (PMID 39472003, 2024). "The anti-PySRA-F2 antibody can protect mice against P. yoelii, and the pro-inflammatory responses such as IL-1β, TNF-α, and IL-6 after infection with P. yoelii are attenuated." (PMID 38624215, 2024). "Numerous studies have examined the impact of IFN-gamma, IL-1β, and TGF-β1 production during the acute stage of infection." (PMID 38967736, 2024). "Analysis of IL1b and IL10 expression revealed that infection of wild-type mouse macrophages NR-9456 with S. epidermidis 1457-M10 and 1457ΔatlE induced a strong IL1b expression, which was slightly lower after infection of TLR9−/− mouse macrophages." (PMID 39567551, 2024). "Mito-TEMPO not only suppressed ROS levels but also reduced both IL-1β release and cell viability in N2aC24L1-3 cells after IAV/WSN infection in a dose-dependent manner." (PMID 39194237, 2024). "Analyses of cytokines gene expression in the ileum showed that EGS infection promoted increased expression of NLRP3, IL-1β, and TNF in WT-infected when compared with WT-uninfected mice." (PMID 39267751, 2024). "When administered after the onset of infection and again 24 h later, MFX effectively reduces cytokine levels—including IL-1β, TNF-α and IL-6—as well as organ lesion markers, such as LDH, ALT and urea." (PMID 39200042, 2024). "PM10 exposure followed by infection significantly increased the protein levels of TNF-α (A), IL-1β (B), and CXCL2 (C), and decreased GPX4 (D) and Nrf2 (E) (p < 0.001 for each)." (PMID 38928968, 2024). "Forty-eight hours after G. parasuis challenge, IL-1β, IL-10, IL-18, TNF-α and IFN-γ mRNA expression was increased, and IL-2 and IL-8 mRNA expression was decreased in the infection group compared to the control group (P < 0.001)." (PMID 39075562, 2024). "Infection of THP-1PMA cells with serial MOIs of RVFV led to release of LDH, accumulation of intracellular PI staining, and IL-1β release in a dose-dependent manner." (PMID 39213434, 2024). "Analgesic treatment did not alter the internal cytokine levels, including IFN-γ, IL-10, IL-1β, and TNF-α, at 24 hours after infection." (PMID 39281680, 2024). "The levels of IL-1β, IL-6, IFN-γ and TNF-α in the PCV4-inoculated group remained elevated throughout the infection period." (PMID 39135875, 2024). "We used Ms-pVV2 and Ms-PE_PGRS38 for infection of RAW264.7 macrophages to study their effects on TNF-α, IL-1β, IL-6, and IL-10 mRNA expression." (PMID 38785795, 2024). "Upon infection, the production of pro-inflammatory cytokines, such as tumor necrosis factor (TNF)α and interleukin (IL)-1β, prime neutrophils to express target antigens that bind with ANCAs." (PMID 38791316, 2024).
infection (continued). "To determine if CETP inhibition regulates proinflammatory cytokine production at the transcriptional level, we examined the mRNA levels of IL-6, IL-1β, and TNF-α using quantitative PCR (qPCR) at 72 hours after infection." (PMID 38646937, 2024). "Overall, our results suggest that Gal‐1 reduces TNF‐α, IL‐6, IL‐1β, MCP‐1, RANTES‐ MIP‐1,α, and IL‐8 secretion in the human fetal membranes stimulated with LPS, mimicking an intraamniotic infection." (PMID 39575516, 2024). "Collectively, these findings indicate that EIIB in L. monocytogenes LIPI-4 stimulates the release of inflammatory factors IL-1β, IL-6, IL-10, and TNF-α to combat infection." (PMID 39057985, 2024). "The literature data are still debatable concerning the precise mechanism of endocan expression in infection, but it is clear that its in vitro expression is stimulated as a result of TNF-α or IL1-β." (PMID 38474287, 2024). "First, IBV DMV/1639 infection exhibited a robust induction of innate immune responses, evidenced by heightened expressions of IFN-α, IFN-β, IL-1β, IL-6, and iNOS mRNA." (PMID 39472003, 2024). "In this study, the levels of IL-1β, IL-6, IL-10, and TNF-α in the sera of mice were measured three days after infection with Lm928, ΔEIIB, and CΔEIIB." (PMID 39057985, 2024). "In order to investigate the role of JTY_0672 in the inflammatory response, we considered the colonization data from organs, and measured the levels of IL-1β, IL-6, TNF-α, and INF-γ in the sera of mice on day 7 after infection." (PMID 39845031, 2024). "LAM increased cell death and IL-1β release, while LAM and ManLAM decreased the killing of Af conidia at early stages of infection in an equivalent manner." (PMID 39605324, 2024). "In contrast, infection of TLR9-/-mouse macrophages NR-9456 with S. epidermidis 1457 elicited a significantly induction of IL1b expression, which was similar to IL1b expression after infection with 1457-M10 and 1457ΔatlE." (PMID 39567551, 2024). "IL-1β, TNF-α, and IL-6 are all upregulated in the context of inflammation and infection and are involved in the pathogenesis of preterm labor." (PMID 38791199, 2024). "Similar to the findings in our transcriptional analysis, we found increased TNFα (P = 0.028) and CXCL1 (P = 0.0056) in the ECRG4 KO mouse infection, as well as a trend towards increased CXCL2, IL1β, and IL6." (PMID 39509414, 2024). "There is an increased recruitment of MHCII-Ly6C+ monocytes to the infection site and an increase in inflammatory mediators such as TNF-α, IL-12, IL-23, IL-1b and IL-6, as well as activation of other inflammatory cells, including Th1 or Th17 cells." (PMID 39081865, 2024). "Particularly noteworthy is the significant contribution of pro-inflammatory cytokines IL-1β (manifesting from the 20th day post-infection) and TNF-α (evident from the 10th day post-infection) to the worsening of neuropathology." (PMID 39766497, 2024). "Our first observation indicated that the presence As during the 6 h infection of S. aureus infection of MAC-T cells led to a dose dependent and significant reduction in IL6, IL1β, IL8 and TNFα produced by the infected cells." (PMID 38414081, 2024). "On the fifth day after infection, a high dose of GUANKE reduced the induction of TNF-α, IL-1β, IL-6, and IL-17." (PMID 39431894, 2024). "Within 3 h of infection, compared to uninfected, WT-infected BMDMs showed 5-fold increased secretion of TNF-a, IL-1β and ~10-fold increase in MIP-1a and IP-10." (PMID 39063103, 2024). "Based on the results, the mRNA levels as well as IL-1β, IL-6, IL-8, IL-10, IL-18, TNF-α and IFN-γ were significantly upregulated, and the IL-2 level was decreased in the infection group compared to the control group (p < 0.05)." (PMID 38582846, 2024). "In this study, the mRNA expression of pro-inflammatory factors, such as IL-1β and TNF-α, in the liver was found to be dramatically increased after infection." (PMID 39597731, 2024).
infection (continued). "Post-infection with uropathogenic Escherichia coli (UPEC), cytokines such as IL-1β, IL-6, and IFN-γ are significantly suppressed, while the bacterial load in the lungs and spleens of wild-type mice is substantially higher than in ATF3 knockout mice." (PMID 38255898, 2024). "This adaptive immunity includes promoting Th1 responses to produce proinflammatory cytokines, such as IL-1β, IL-18, IL-12, tumor necrosis factor (TNF-α), and interferon (IFN)-γ to effectively clear the infection." (PMID 38623843, 2024). "IL-10 was significantly increased in CC061 mice after MRSA infection, while IL-1β, IL-4, IL-9, IL-18, IL-23, and IL-27 were significantly increased in CC024 mice after infection." (PMID 39178306, 2024). "PA14 infection induced significant increases in IL-6, TNF and IL-1β in the PA14 + PBS group compared to the Control + PBS group in both lung and BALF." (PMID 39062025, 2024). "Our report is the first to show the expression profile of inflammatory biomarkers (IL-1β, IL-6, TNF-α, IL-18) in four tissues after infection with L. europaeus—with two genotypes simultaneously." (PMID 39273479, 2024). "Inflammasomes serve as a platform for the activation of caspase 1, an enzyme that cleaves proinflammatory cytokines, interleukin 1β (IL1β) and IL18, converting them into their active forms during an infection by M. tb." (PMID 39125766, 2024). "In contrast, infection with the Omicron, yielded a slight increase in TNF-α secretion with less amount of IL-1β and Interleukin 2 (IL-2) compared to wild-type." (PMID 38568894, 2024). "IL-1β and IL-18, elevated in CC024 mice after infection, act on lymphoid cells and enhance the production of IL-22." (PMID 39178306, 2024). "Early after infection (day 4 PI), plasma levels of IFN-γ, TNF-α, IL-3, IL-17, IL-1β, and IL-4 were increased in baso IL-18R (−) mice but not in basophil-depleted mice." (PMID 38780542, 2024). "Our investigation showed that S. suis strains of cps2, 14, and 9 induced IL-1β and TNF-α following in vitro infection of porcine blood as previously reported in human whole blood." (PMID 38317258, 2024). "This interleukin induces the production of TNF-a and IL-1β, as well as CXC chemokines involved in the recruitment and activation of Mφ and neutrophils in various models of infection." (PMID 38248954, 2024). "TNF-α, IFN-γ, IL-1β, IL-6, and MIF are pro-inflammatory molecules that activate immune cells and defend against infection." (PMID 38572322, 2024). "In previous studies, a single application or mixture of probiotics has shown the reduction of proinflammatory cytokines including IFN-γ IL1B, IL2, IL8, and TNF-α in various animal species and cell lines after pathogen-induced infection." (PMID 38561808, 2024). "In the control macrophages, infection by both Mtb HN878 and CDC1551 upregulated the percentage of TNF-α + and IL-1β + cells (middle and right columns)." (PMID 38980014, 2024). "On gene expression level, age-dependent differences only were observed for Tnf and Il1b of PAO1-infected lung slices and Il17a after infection with either of the two bacterial strains." (PMID 38178102, 2024). "In DLD-1 cells, the expression of IL-1β and IL-8 were upregulated while TNF-α and IL-6 expression were downregulated after LV infection." (PMID 39427065, 2024). "An increase in pro-inflammatory cytokine production was detected in homogenized lung supernatants including IFN-γ, IL-1β, IL-6, IL12-p40 and IL-17 at three- and four-weeks post-infection." (PMID 38198478, 2024). "Under pathological conditions such as stress, infection, or neurodegenerative diseases, pro-inflammatory cytokines, including tumor necrosis factor alpha (TNF-α), interleukin-1 beta (IL-1β), and interleukin-6 (IL-6), are released in excess." (PMID 39517142, 2024). "Using a human cervical tissue explant model, we found that GC inoculation increased the local secretion of both proinflammatory (IL-1β and TNF-α) and antiinflammatory (IL-10) cytokines during the first 24 hours of infection." (PMID 39585777, 2024).
infection (continued). "The expression of cytokine and chemokine genes, IL-1β, IL-6, TNF-α, IFN-γ, IL-12, and CXCLi1 in the liver of chickens were detected 3 to 5 days post-infection." (PMID 38846788, 2024). "Compared to the control group, the expression levels of IL-1β, IL-6, and TNF-α in the PCV4-inoculated group continuously increased during the infection period, peaking at 21 days." (PMID 39135875, 2024). "Post-infection, RTX-treated mice showed reduced inflammatory cytokine levels, including IL-1β, IL-6, and TNF." (PMID 39414787, 2024). "IL-1β, IL-12 (p40), IL-4, and CCL3 levels were modulated, showing significantly lower induction during early infection (1–9 h) followed by a significant increased after 12 h." (PMID 38538626, 2024). "Upon infection, the EBV dUTPase protein induces the expression of pro-inflammatory cytokines such as IL-6 and IL-1β in microvascular endothelial cells and microglia, as well as TNF-a in astrocytes." (PMID 38248274, 2024). "To investigate the impact of CASK on cytokine production, we measured the levels of IFN-β, IFN-α, IFN-6, TNF-α, IL-6, IL-1β and IP-10 in the culture supernatant of macrophages at 12 h post-H5N1-IAV (MOI=1) infection." (PMID 39850902, 2024). "Studies have shown a positive regulation of the gene expression of pro-inflammatory cytokines (IL-1β, TNF-α, and IL-6) in human macrophages after infection with L. amazonensis and L. major." (PMID 39199338, 2024). "We found Trim26–/–mice had higher levels of proinflammatory cytokine expression than Trim26+/+ mice, including IL-6, IL-1β, and TNF-α at day 5 post-infection." (PMID 38166150, 2024). "The prepared ODHP-NS-HG reverted the inflammatory effect and suppressed the infection by compromising the levels of COX-2, TNF-α, NF-κB-p105, IL-6, and IL-1β in treated group E comparing to untreated groups." (PMID 38217256, 2024). "In conclusion, we showed that in a mouse model of Pm infection, GA significantly reduced Pm-induced vascular inflammatory injury, and decreased PARP1, HMGB1, IL-1β, and IL-18 protein expression in vascular tissue." (PMID 39850582, 2024). "During primary infection of KSHV in endothelial cells, B cells in Kaposi’s sarcoma endothelial and primary effusion B-cell lymphomas can secrete IL-1β and IL-18 upon caspase-1 activation." (PMID 38177104, 2024). "We observed that infection of CD18−/− BMDMs with the control strain induced lower levels of the cleaved form of caspase-1, IL-1β, and N-terminal Gasdermin D (N-GSDMD) compared to infection of WT BMDMs." (PMID 38724513, 2024). "Monocytes travel throughout the bloodstream, detecting and responding to infections or other stimuli by producing inflammatory cytokines such as TNF-α, IL-1β, IL-6, IL-8, IL-10, and IL-12." (PMID 39042701, 2024). "M1 macrophages are pro-inflammatory macrophages that clear pathogens and produce inflammatory mediators such as IL-1β, IL-6, and TNF-α during infection and inflammatory responses." (PMID 39123188, 2024). "Exposure to PM10 followed by infection significantly elevated relative mRNA levels for TNF-α, IL-1β, CXCL2, TLR4, IL-6, COX2, and iNOS when compared to control air (p < 0.001 for all)." (PMID 38928968, 2024). "During in vivo infection, pigs infected with highly virulent strains of ASFV exhibit elevated systemic production of IFN, TNF-α, IL-1α, IL-1β, and IL-6, mainly facilitated by NF-κB or alternative transcription factors." (PMID 38846950, 2024). "Inflammatory genes also contribute to the viral pathogenesis, we also compared the mRNA expression of inflammation factor, including il-1β, il8, tnfα, between mylipb-/- and WT larvae following SVCV infection." (PMID 38739631, 2024). "Local production of cytokines, such as IL1β, IL6 and TNFα help amplify this proinflammatory response, while potent chemokines guide the neutrophils to the infection." (PMID 39509414, 2024).